CD4 (CD4 molecule)
Diseases named in the same sentence as CD4 in open-access papers (continued):
Sharing a sentence is not in itself a finding about the gene and the disease.
infection (continued). "At 200 days post-infection, we predict the CD4 count to be 70 cells/μL for the rapid-progressor morphine group and 152 cells/μL for the slow-progressor morphine group, while in the control group it is maintained at 185 cells/μL." (PMID 30931971, 2019). "Cytotoxic CD4 T lymphocytes have been shown to play a protective role in several infections including M. tuberculosis." (PMID 31627457, 2019). "In this study, we explored the CD4+ T cell response to primary RO and IVag infection with ZIKV using LysMCre+Ifnar1fl/fl mice, in which the type I IFN receptor is absent from myeloid cells but present on T and B cells." (PMID 30677097, 2019). "C57BL/6 mice that receive a single high dose infection develop resistance, dependent on CD4+ Th2 cells and IL-13 production." (PMID 31730667, 2019). "The cell-free infection from Jurkat cells (it was important to keep lymphoid origin of producer cells) to Raji/CD4 target cells was set up by transfecting Jurkat cells in a large scale to generate VLPs in amount sufficient for infectivity detection." (PMID 31027334, 2019). "Antibodies specific for CD4-bound HIV Env that can destroy cells in different stages of infection, despite changes in epitope availability and amount of CD4-bound targets, are likely to confer the greatest level of protection against HIV." (PMID 30903381, 2019). "The degrees of reliance on subsets of CD4 helper T cells in overcoming infection differ between males and females, where the levels of Th1 and interferon gamma (IFN-γ) responses in females have been reported to be higher than those in males." (PMID 30918059, 2019). "We used HIV-1 Gag p24 levels in culture supernatants over time as a measure of productive infection in CD4+ T cells." (PMID 31304185, 2019). "In this cohort of 55 Singaporean patients, viremic patients in the acute phase of infection had reduced numbers of immune cells in their blood (including CD4 and CD8 T cells), and higher production of IFN-γ." (PMID 31382545, 2019). "The IFN-γ producing lymphocytes after antigen stimulation were found in CD4−CD8+ and CD4+CD8+ subsets of all immunized groups 7 days after infection." (PMID 31447829, 2019). "Here, for the very first time, we show that CECs regardless of source (cord blood, placenta, or peripheral blood of anemic and HIV patients) mediate the exacerbation of HIV-1 replication in CD4+ T cells and HIV trans-infection of CD4+ T cells." (PMID 31772057, 2019). "CD4 T cell memory is fundamental for long-lasting immunity and effective secondary responses following infection or vaccination." (PMID 32010148, 2019). "Our studies show that CD4 T cells specific for epitopes derived from HA are the most effective in providing help for the HA-specific B cell responses to infection and vaccination." (PMID 31694141, 2019). "In the CD8 response, HCV-specific CD8 T-cells are also detectable in most subjects early on, typically at higher frequency than their CD4 counterparts, and their appearance in early infection often coincides with some level of control of HCV viremia." (PMID 31357397, 2019). "After detailed analysis of the CD4+ TRM protein profile in these mucosal tissues, which predicted increased susceptibility and long-term persistence, we show preferential infection of these cells using a cervical ex vivo model of HIV infection." (PMID 31628331, 2019). "Recovery of IFN-γ production at the late stage of infection in the CD4+ T cell-depleted group was presumed to be due to complementation by other cells." (PMID 31608052, 2019). "These values were then incorporated into a model for CTL-mediated HIV control and the effects on CTL frequencies, viral loads and CD4 T cell counts were predicted for different infection phenotypes." (PMID 31693657, 2019). "Parasite-specific CD4+ T cells have previously been observed in natural and experimental infection studies." (PMID 30323025, 2019).
infection (continued). "Results showed that peripheral CD4+ T cells decreased rapidly in infected hu-PBL mice with viral detection in all tissues within 3 days of infection." (PMID 30873181, 2019). "The second phase of HIV-1 transmission is believed to imply DC productive infection, which, although less efficient than in CD4+ T cells, has a key role in long-term HIV-1 transmission." (PMID 31708924, 2019). "Previous studies have shown that LdCen−/− infection of BMDCs results in robust proliferation of OT-II CD4+ T cells." (PMID 31608064, 2019). "For example, inhibited infection through in vivo depletion of CD4 + -FOXP3+ T Regulatory and Th17 subset populations, and aided in clearance of persistent H. pylori colonization." (PMID 31138331, 2019). "In contrast to the diversity in specificity and functionality elicited by CD4 T cells in response to infection, vaccination with licensed vaccines is currently designed to elicit HA-specific neutralizing antibodies." (PMID 31134060, 2019). "In addition, low CD4+ count was significantly associated with a higher infection rate with microsporidia (28.6% vs. 8.1%), where patients with counts < 200 cells/μl were at about 4.5-fold higher risk of infection than those with counts ≥200 cells/μl (OR = 4.55; 95% CI = 1.066–7.297, P = 0.037)." (PMID 31142275, 2019). "Filoviral trans-infection from DCs to CD4+ T cells is improbable as lymphocytes are largely resistant to EBOV infection." (PMID 31861617, 2019). "Although infection of A1Ifnar-/- mice, and in some cases A1Ifnar+/+ mice, led to high level viremia and profound CD4+ T-cell depletion, in all cases RhIV infection was apparently cleared." (PMID 31644426, 2019). "In fact, IL-17-producing Th17 cells are considered to be particularly essential in vaccine-mediated immunity by rapidly recruiting CD4+IFN-γ+ T-cells to the site of infection, leading to earlier control of Mtb35." (PMID 31664157, 2019). "Here, we showed that upon infection of the control and vaccine 1 group, CD4+CD8+ T cells secreted IFNγ upon TLA stimulation in a bimodal response, while in the vaccine 2 group this IFNγ production by CD4+CD8+ T cells gradually increased until D96 of the study." (PMID 31620134, 2019). "Results showed that inhibition of miR-21 by LNA-oligonucleotides significantly increases the CD4+CD44+ 2W+ T cell population compared to untreated LdWT2W infection." (PMID 31608064, 2019). "CD11c+ DCs and CD4+ T cells were isolated 2 days after infection from MLNs to determine DCs activation, TH17 polarization, and Ifnγ mRNA expression by T cells." (PMID 31840109, 2019). "Although we observed similar impacts using TcR transgenic and polyclonal CD4 T cells, a comprehensive understanding of how and when IL-2 produced by CD4 T cell populations impacts infection requires further study." (PMID 31412088, 2019). "Essential virological and immunological processes such as the activation and mass destruction of CD4+ T cells and the establishment of viral reservoirs are developed during early stages of infection." (PMID 31680987, 2019). "Cathepsin B activity in SAOS-2, HeLa, and TE671 cells was responsible for HIV-1 envelope glycoprotein gp120 degradation in acidic endosomes, contributing to reduced CD4-independent infection." (PMID 31077130, 2019). "C57BL/10 mice depleted of CD4+ T cells and infected using an intranasal infection of M. avium clearly support a role for CD4+ T cells." (PMID 30763316, 2019). "The three cases reclassified on the basis of a CD4 count less than 200 cells/mm3 also had other information indicating longstanding infection." (PMID 30869051, 2019). "The minimal importance of Vpr in infection of activated CD4+ T cells in vitro suggests that its major importance lies in overcoming restriction to virus replication in non-cycling myeloid cell populations, such as macrophages and dendritic cells." (PMID 31396206, 2019).
infection (continued). "Activation-induced markers (AIM) were used to identify antigen-specific T cells in a cytokine-independent assay, to detect vaccine and natural infection-induced CD4 T cell responses." (PMID 31443439, 2019). "We further found that AE-specific CD8 T cells promoted viral trans-infection from mature DCs to CD4 T cells, suggesting a mechanism by which HIV-1 adaptation confers a viral advantage other than direct immune evasion." (PMID 31398241, 2019). "IL-15 boosts the immune response to infection by activating NK cells and enhancing priming of CD4/CD8 cells in terms of IFN–r production in patients with TB." (PMID 30760247, 2019). "To validate our RNA-Seq results at the protein level, we used a flow-cytometry-based approach to quantify cytokine concentrations in the culture supernatants of CD4 +T cells at day three post-infection." (PMID 30717826, 2019). "In regard to other immune regulators, regulatory T (Treg) cells are a subset of CD4+ T cells that regulate the host response to infection by inhibiting the effecter functions of CD4+ and CD8+ T cells." (PMID 31126067, 2019). "Here, we investigated the CD4+ T cell response to primary intravenous and intravaginal infection with ZIKV." (PMID 30677097, 2019). "This can be explained, in part, by delays between infection and CD4 decline: people with low CD4 counts will, on average, be older than people with high CD4 counts." (PMID 31846456, 2019). "AHR knockdown significantly impaired HIV-luc/JRFL infection of Magi/CCR5 cells, HIV-luc/VSV-G infection of HEK293T cells (unpaired t test, P < 0.001), and HIV-luc/NL4-3 infection of primary CD4+ T cells (unpaired t test, P < 0.01)." (PMID 31848275, 2019). "Our data confirms the findings of a previous report that indicated that envelopes of transmitted/founder or control/reference viruses have similar infection patterns of CD4+ T-cells in human cervical tissue ex vivo." (PMID 31437197, 2019). "Total CD4+ T cell counts were measurably reduced at one-week post infection for 7 of the 9 infected animals." (PMID 30943274, 2019). "Binding to DC-SIGN on dendritic cells (DCs) can result in viral transport to local lymphoid tissue leading to infection of CD4+ T cells." (PMID 31031768, 2019). "For instance, two recent independent reports indicated that in the periphery, CD4+ T cell counts were inversely correlated with high serum levels of glutamine and glucose, suggesting a role of these metabolites early on in infection and viral spread." (PMID 30850623, 2019). "Distinct from HCV, HIV establishes infection within CD4 expressing immune cells such as CD4+ T lymphocytes and macrophages." (PMID 31260499, 2019). "While the bulk of IST staining has been done using MHCI tetramers to study the CD8+ T cell response, MHCII tetramers are available to investigate the CD4+ T cell response to infections and autoimmunity." (PMID 31635220, 2019). "Lymphocytic involvement during the late phase of infection was also proven by CD4T/CD8T ratios (CD3+CD4+/CD3+CD8+), greater in infected animals with both swine (0.59) and Human HEV-3 (0.69) than in control group (0.012)." (PMID 31211801, 2019). "In mouse models of schistosome infection, CD4+ T cells also play an enigmatic role in the development of schistosomes during the pre-patent period of infection, i.e., prior to the onset of oviposition." (PMID 30653492, 2019). "For instance, in the RV144 trial, CD4+ T-cells secreting IL-2, TNF-α, IFN-γ, IL-4, and CD154 in response to HIV-1 envelope peptides were associated with lower infection rates in vaccine recipients." (PMID 31382453, 2019). "Although not significantly different, rhesus macaques had a distinct elevation in their activated CD4 T cells at day 9 post-infection (p = 0.174) and approached significance at the time of SMA in rhesus macaques (p = 0.08)." (PMID 31831787, 2019).
infection (continued). "Further studies in LysMCre+IFNARfl/fl mice have described a similar Th1 CD4 T cell response to what was observed in immunocompetent mice, as well as a T follicular helper (Tfh) cell response from 7 days post-infection (dpi) onward." (PMID 31382545, 2019). "We demonstrate that CECs from human cord blood or placental tissues in a dose-dependent manner exacerbate HIV-1 replication and infection, by both R5- and X4-tropic viral strains, in autologous CD4+ T cells." (PMID 31772057, 2019). "The CD8+ T response is enhanced via the assistance of CD4+ T cells during the acute stages of infection." (PMID 31027278, 2019). "Treg depletion before a TMEV-BeAn infection using anti-CD25-antibodies results in increased CD4+ and CD8+ T cell responses, which reduces the viral load and delays the onset of clinical diseases." (PMID 30669615, 2019). "A significant correlation was observed between cytokine expression by CD4 T cells and delayed infection." (PMID 31413132, 2019). "Replacing the CD4 transmembrane domain with the CD8 hinge region resulted in slightly less expression, but rendered the HIV CAR T cells less susceptible to infection and improved the overall efficacy of these T cells." (PMID 31611880, 2019). "An array of C-type lectins (CLR) expressed on myeloid cell lineages have been shown to successfully capture HIV-1 and pass the virus to activated CD4+ T-cells, referred to as trans-infection." (PMID 31487324, 2019). "Elevated LPS levels measured early in infection predicted accelerated CD4+ T cell decline, as well as immune activation and exhaustion." (PMID 31449552, 2019). "Intranasal infection was also shown to activate CD4+ helper T cells in the NALT more robustly than in draining lymph nodes and the spleen, where there was little to no activation." (PMID 31119108, 2019). "Primary infection with E. muris promoted polarization of memory CD4 Th1 cells and memory-like NK cells in the spleen and liver at day 28 post-infection." (PMID 31134081, 2019). "As an alternative means to measure the level of activation in CD4+ T cells, infection with the CXCR4‐tropic HIV‐1 NLX virus was chosen as a biological model system." (PMID 31552706, 2019). "We further analyzed the correlation between peripheral CD4+T cells and infection-related indicators in infectious SLE patients." (PMID 30994732, 2019). "CD4+ T cells play critical roles in coordinating immune responses during infection by differentiating into functional subsets best suited to control pathogen growth." (PMID 30809232, 2019). "Entry into latency is established soon after HIV transmission, either by infected activated CD4+ T cells reverting back to a resting state or through the direct infection of resting CD4+ T cells." (PMID 31616431, 2019). "We previously reported that HIV-1 trans infection of CD4+ T cells by DC and B cells results in highly efficient virus replication in CD4+ T cells, as measured by levels of HIV-1 Gag p24 over 12 days of co-culture." (PMID 31304185, 2019). "While ILC2 production of IL-13 alone appears to be sufficient to support this macrophage population, ILC2s depend on IL-2 from CD4+ T cells to survive and mediate these effects during infection." (PMID 31072011, 2019). "We also showed for the first time a protective effect of CTX prophylaxis on TM infection in this population, and showed that protective effect was more profound in patients with a CD4+ cell counts <50 cells/μL." (PMID 31851879, 2019). "By 7 days post-infection, ~25% of infected memory CD4 T cells were p24+CycT1-, and ~16% were p24+CycT1+ (N = 3)." (PMID 30786885, 2019). "Each symbol type on each chart represents an individual mouse (n = 2 to 4 for each virus/mouse strain combination) (G) Blood CD4+ T-cell proportion (% of CD3+ cells) in A1Ifnar-/- mice at the indicated times following infection with RhIVCH505." (PMID 31644426, 2019).
infection (continued). "Second, pDCs release chemokines such as CCL5 that recruit CCR5+ CD4+ T cells to the site of infection and thus facilitate the spread." (PMID 31708924, 2019). "Ceci pourrait s'expliquer par le fait que ces plus dépendants au tabac avaient un moins bon contrôle de l'infection avec un taux de CD4 <350 éléments/ml chez 80% d'entre eux (n=11)." (PMID 31762909, 2019). "The adoptive hosts were challenged with virus to investigate the mechanisms by which memory CD4 T cells participate in clearing infection." (PMID 30641955, 2019). "In our study, the baseline CD4+ cell count was identified to be a major factor influencing TM infection." (PMID 31851879, 2019). "Feeding GF animals LPS alone, led to similar increases in cell number in the CNS of infected mice, more MHCII expressing microglia and increased CD4 T cell trafficking to the CNS during infection." (PMID 31309928, 2019). "Infection of these transgenic mice with RhIVs results in rapid, specific depletion of CD4+ T-cells and an acute viremia that resolves, followed by development of antibodies directed against the HIV-1 envelope." (PMID 31644426, 2019). "Mac-tropic HIV-1 evolves enhanced CD4 interactions that enable macrophage infection via CD4, which is in low abundance." (PMID 30415390, 2019). "In the spleen, there was a reduction in the proportion of CD4+ T cells and an increase in B cells at days 8–10 post-infection as well as a marked increase in the proportion of myeloid cells at d12 post-infection." (PMID 31676877, 2019). "Following a third challenge with RhIVSF162 at 84 days (Expt#2) or 91 days (Expt#1 and Expt#3) after the first infection, plasma viremia was undetectable, and only minor perturbations of CD4+T cell numbers were observed." (PMID 31644426, 2019). "The CS5-specific CD4+ T cell and antibody responses were still significantly elevated one year after experimental infection." (PMID 31665141, 2019). "In the later clinical or chronic phase of the disease, CD4 T cells start to appear in the cornea around day 6–7 post-infection, a stage when virus is usually already cleared from the cornea." (PMID 30941142, 2019). "In this study, we demonstrated by flow cytometry that resting CD4+ T cells are subject to productive infection." (PMID 31036079, 2019). "Intracellular staining for IFN-γ expression by ovalbumin-specific mucosal CD4+ T cells in WT mice after OVA-Citrobacter infection demonstrated that CD4+ T cells are a major source of Citrobacter-induced IFN-γ following infection in the intestine." (PMID 30818341, 2019). "Although proliferation of the 2W specific CD4+ T cell population was observed in LNA treated LdWT infection, expression of other markers of early memory such as IL-7R were absent in this population." (PMID 31608064, 2019). "This was also reflected in the similar IgG response seen at day 18 post-infection, which is a key indicator of Th1/2 balance, and IL-9 expression in mLN CD4+ T-cells at day 13 post-infection." (PMID 30998782, 2019). "Because it is difficult to study infection in unadapted SHIVs that lack mutations that have been identified to enhance macaque CD4 use, we cannot draw conclusions on whether efficient engagement of macaque CD4 also affects IFITM-mediated restriction in macaques." (PMID 31260493, 2019). "A recent report showed that 2 antiretroviral drugs, tenofovir and raltegravir, were ineffective in blocking DC-mediated HIV-1 trans infection of CD4+ T cells in vitro." (PMID 31304185, 2019). "Taken together, our data suggests that the emergence of AE-specific CD8 T cell responses in CHI confers a selective advantage to the virus by promoting DC-mediated CD4 T cell trans-infection." (PMID 31398241, 2019). "Our results imply that the improved protective efficacy of the Il2-/- memory CD4 T cells in the adoptive transfer model employed here is due largely to differences in the inflammatory response generated upon infection." (PMID 31412088, 2019).